ENSG00000253372 (novel transcript)
Gene: Long non-coding RNA gene on chromosome 8 (122,807,746 to 122,816,517, forward strand). Ensembl gene ENSG00000253372.
Gene Ontology:
Biological process: miRNA-mediated post-transcriptional gene silencing